PKP2 (plakophilin 2)
Diseases named in the same sentence as PKP2 in open-access papers (continued):
Sharing a sentence is not in itself a finding about the gene and the disease.
heart failure (16 papers, 2012 to 2026). Inability of the heart to pump blood at an adequate rate to meet tissue metabolic requirements. "Arrhythmogenic cardiomyopathy (ACM) is a genetic form of heart failure that affects 1 in 5,000 people globally and is caused by mutations in cardiac desmosomal genes including PKP2, DSP, and DSG2." (PMID 42090754, 2026). "Arrhythmogenic cardiomyopathy (ACM) is a genetic form of heart failure that affects 1 in 5000 people globally and is caused by mutations in cardiac desmosomal proteins including PKP2, DSP, and DSG2." (PMID 39763850, 2024). "ARVC patients with PKP2 mutation are less likely to present left ventricular involvement and heart failure symptoms." (PMID 34191271, 2021). "ARVC patients with PKP2 mutation are less likely to have left ventricular involvement and heart failure symptoms." (PMID 34191271, 2021). "Overall, variants in DSG2 appear to generate a more severe form of ACM with more severe ventricular dysfunction, associated with a higher risk of heart failure in comparison to PKP2-linked ACM." (PMID 32466575, 2020). "In mutation positive ARVD/C, DSP carriers are associated with four-fold higher likelihood of sudden cardiac death, LV dysfunction, and heart failure compared to PKP2 carriers." (PMID 34011348, 2021). "Although severe heart failure in ARVC is rare, carriers for a PKP2 variant alongside a second ARVC variant were the most likely to suffer severe RV dysfunction and require heart transplant." (PMID 32466575, 2020). "This role of Cx43 hemichannel-mediated calcium entry in PKP2-cKO arrhythmogenesis is also consistent with recent studies showing its pro-arrhythmic effect, and has been reported in other conditions such as heart failure and muscular dystrophy." (PMID 34630150, 2021). "The proband with PKP2 genetic variant had a clear, RV-dominant ACM and a classical arrhythmic presentation, whereas his niece with the same genetic variant had a biventricular disease, with anteroseptal LV fibrosis and heart failure presentation." (PMID 33238575, 2020). "Through comparison studies, they found that patients with a PKP2 mutation were younger at diagnosis, more often had negative T waves, had higher left ventricular ejection fracts, and were less likely to have symptoms of heart failure than ACM patients without PKP2 mutations." (PMID 37895213, 2023). "Moreover, we found that ARVC patients with a PKP2 mutation present less frequently left ventricular damage progression and symptoms of heart failure than subjects without PKP2 mutation." (PMID 34191271, 2021). "In the present study, PKP2, DSG2, and DSC2-KOs experiment with a decrease in ATPase expression (codified for SERCA), indicating that the absence of those genes may be linked to heart failure, a clinical feature present in ACM phenotype." (PMID 36768439, 2023). "However, here we detect distinct myocardial transcriptomic profiles in patients affected with different genetic cardiomyopathies in refractory heart failure (stage D) stratified by the affected genes (LMNA, PKP2, RBM20 and TTN) and not based on the clinical phenotype (DCM or ARVC)." (PMID 33260757, 2020).
Brugada syndrome (15 papers, 2017 to 2025). A genetically heterogeneous condition characterized by complete or incomplete right bundle branch block accompanied by ST elevation in leads V1-V3. "Clinically, mutations in PKP2 are frequently observed in patients with congenital arrhythmias, such as arrhythmogenic cardiomyopathy, Brugada syndrome, and idiopathic ventricular fibrillation." (PMID 41468454, 2025). "In the treatment of Brugada syndrome, Adeno-associated virus serotype rh.10 encoding for the human PKP2 gene (AAVrh.10hPKP2) therapy, which is being tested in multiple clinical trials in the United States in 2024." (PMID 39845823, 2024). "Mutations in the PKP2 gene have also been associated with the onset of other pathologies, such as Brugada syndrome (BrS)." (PMID 38473714, 2024). "Several PKP2 mutations were previously identified in five unrelated individuals diagnosed with Brugada syndrome." (PMID 32992720, 2020). "Recently, the PKP2 p.S183N mutation was found in a patient affected by Brugada syndrome (BS), an inherited arrhythmic channelopathy most commonly caused by sodium channel gene mutations." (PMID 32443836, 2020). "These interactions between the cardiac sodium channel complex and the intercalated disc likely underline mechanisms relevant to SCN5A-medicated ARVC and PKP2-mediated Brugada syndrome." (PMID 31336969, 2019). "Abnormalities such as epsilon waves and right ventricular dilation, considered classical hallmarks of ACM, have been described recently in patients with Brugada syndrome, along with mutations in the PKP2 gene." (PMID 29940860, 2018). "The loss of PKP2 has been associated with Nav1.5 reduced functionality, both in PKP2 heterozygous knockout mice and in Brugada syndrome patients, who carry a PKP2 mutation." (PMID 28679668, 2017). "The electrocardiographic pattern also resembles the pattern observed in Brugada syndrome, which is also associated with the PKP2 mutations." (PMID 28253841, 2017). "PKP2 variants lead to phenotypes that vary from purely arrhythmogenic to severe mechanical dysfunction and therefore pkp2 alterations are also linked to inherited cardiac conditions as Brugada syndrome and Catecholaminergic polymorphic ventricular tachycardia (CPVT)." (PMID 31438494, 2019). "Recently, alterations in the Pkp2 gene have been associated with different inherited cardiac conditions including Arrythmogenic Cardiomyopathy (ACM or ARVC), Brugada syndrome (BrS), and idiopathic ventricular fibrillation to name the most relevant." (PMID 30619891, 2018). "Furthermore, these findings should encourage the inclusion of PKP2 as part of routine genetic testing for Brugada syndrome, in particular, to promote a better understanding of the key players participating in the molecular mechanism of this disorder." (PMID 32992720, 2020).
dilated cardiomyopathy (11 papers, 2013 to 2025). "A recent large-cohort analysis using high-throughput sequence analysis has highlighted the high levels of PKP2 mutations in patients diagnosed with dilated cardiomyopathy." (PMID 35063130, 2022). "For example, mutations in JUP, DSP, PKP2, DSG2, DSC2, CTNNA3, CDH2, or PLN (all of them more abundant in LV) predominantly lead to arrhythmogenic right ventricular cardiomyopathy, and mutations in MYH7, HSPB7, NEXN and MYPN (also all more abundant in LV) lead to dilated cardiomyopathy." (PMID 32291283, 2020). "We examined plakophilin-2, desmoglein-2, desmocollin-2, plakoglobin and β-catenin protein expression levels from seven independent ARVD/C heart samples compared to two ischemic, five dilated cardiomyopathy and one healthy heart sample as controls." (PMID 24086444, 2013).
Right ventricular cardiomyopathy (7 papers, 2014 to 2024). Right ventricular dysfunction (global or regional) with functional and morphological right ventricular abnormalities, with or without left ventricular disease. "Also of interest is the plakophilin 2 gene (PKP2), associated with right ventricular cardiomyopathy and multiple genes involved in mitochondrial energy metabolism (MTCH1, OXA1L, MUL1)." (PMID 27923400, 2016).
lung carcinoma (6 papers, 2020 to 2025). "In terms of potential mechanism, PKP2 could regulate the activity of Wnt/β-catenin in colon cancer-associated fibroblasts, and PKP2 promoted the proliferation and migration of lung cancer by activating EGFR signaling pathway." (PMID 33088217, 2020). "For example, PKP2 has been identified as a critical driver of radiation resistance in lung cancer, and its expression was significantly higher after irradiation than before irradiation." (PMID 37056929, 2023). "PKP2 has been verified overexpressed in several types of human cancers including lung cancer; it is an unfavorable prognostic biomarker for LUAD patients but not for LUSC patients." (PMID 35186082, 2022). "Research suggests that the PRMT1 inhibitor C‐7280948 may enhance the radiosensitivity of lung cancer by modulating the PRMT1/PKP2/β‐catenin/LIG4 signaling pathway, thereby overcoming radiation resistance and improving patient outcomes." (PMID 41256732, 2025). "Similarly, PKP2 (Plakophilin 2) and DERL1 (Derlin 1) are overexpressed in lung cancer cells, promote the development of lung cancer, and are associated with lung cancer prognosis." (PMID 37328788, 2023). "PRMT1 can promote methylation of plakophilin 2 (PKP2) to increase its interaction with β-catenin, leading to β-catenin stabilization and activating LIG4 in lung cancer cells." (PMID 40001953, 2025). "Additional mechanisms include PRMT1‐mediated methylation of PKP2 and SOX2, which contributes to radioresistance and chemoresistance in lung cancer." (PMID 41256732, 2025).
myocarditis (6 papers, 2019 to 2024). Myocarditis is a condition that is characterized by inflammation of the heart muscle (myocardium). "In this view, it is interesting to highlight the role of e.g. DSP, DSG2 and PKP2 mutations in acute (recurrent) myocarditis." (PMID 39347728, 2024). "The incidence of potentially harmful mutations in the genes DSP, PKP2, and TNNI3 (encoding, respectively, desmoplakin, plakophilin-2, and troponin I type 3) is elevated in children with acute myocarditis." (PMID 37456487, 2023). "Although these studies used DSP disruption as its genetic model of myocarditis, many other genes have been implicated in this process, including TTN, LMNA, FLNC, PKP2, and others." (PMID 38768074, 2024). "The question remains as to whether PKP2 and the inflammatory/immune response are transcriptionally linked in adult cardiac myocytes, in such a way that PKP2 deficiency endogenously (without a pathogen as trigger) activates a transcriptional program that can lead to a “sterile myocarditis” phenotype." (PMID 33536940, 2020). "Cardiac pressure overload and auto-immune myocarditis drive (subepicardial) pro-fibrotic mechanisms in the PKP2 happloinsufficient heart." (PMID 31438494, 2019). "Overall, we show that PKP2 transcriptionally activates pathways that can mimic phenotypes reminiscent of myocarditis without necessarily being activated by a pathogen, in other words, a sterile myocarditis." (PMID 33536940, 2020).
channelopathy (5 papers, 2015 to 2024). Channelopathies are a group of diseases caused by the dysfunction of ion channel subunits or their interacting proteins. "Instead, PKP2 may be a gene that can, if mutated, precipitate phenotypes that vary from purely arrhythmogenic (a “channelopathy”) to that of a severe mechanical dysfunction." (PMID 28740174, 2017). "The variants included three channelopathy-associated genes (RYR2, CACNA1C, and ANK2), three HCM- or DCM-associated genes (MYH7, LDB3, and PRKAG2), five ACM-related genes (PKP2, JUP, DSG2, DSP, and TMEM43), and two cardiac transcription factor genes (TBX5 and GATA4)." (PMID 39272661, 2024).
muscular dystrophy (5 papers, 2013 to 2024). Muscular dystrophy (MD) refers to a group of more than 30 genetic diseases characterized by progressive weakness and degeneration of the skeletal muscles that control movement. "The PKP2 gene, also known as Plakophilin 2, has a role in cell adhesion and may be upregulated in muscular dystrophies as a protective reaction to cellular stress and damage, in an effort to preserve cellular integrity." (PMID 39415830, 2024).
ovarian carcinoma (5 papers, 2020 to 2024). A malignant neoplasm originating from the surface ovarian epithelium. "Univariate and multivariate analysis showed that high PKP2 expression (HR = 3.117, 95% CI = 1.146–8.478, P = 0.026) and lymph node metastasis (HR = 3.682, 95% CI = 1.6–8.476, P = 0.002) were independent risk factors for prognosis of patients with ovarian cancer." (PMID 33088217, 2020). "PKP2 was elucidated to initially affect tumorigenesis, aggressiveness, malignant biological behavior, and immune infiltration of ovarian cancer." (PMID 35403268, 2022). "Aberrantly expressed PKP2 has been found in a number of tumors, including bladder, osteosarcoma, and ovarian cancers." (PMID 36276289, 2022). "High PKP2 expression was reported to be involved in the development of various cancers, including bladder, lung, and ovarian cancers." (PMID 34949159, 2022). "A total of 117 cases of ovarian cancer tissues were divided into low (−/ +) and high (+ + / + + +) PKP2 expression groups." (PMID 33088217, 2020). "The expression level and prognosis of PKP1 showed little significance in ovarian cancer, and the expression of PKP2/3 mRNA and protein were upregulated in OC, showing significant correlations with poor prognosis of OC." (PMID 33088217, 2020). "We further identified that PKP2/3 could participate in a variety of biological functions, signaling pathways and immune infiltration, which provided novel and valuable insights into the molecular mechanisms underlying the initiation and progression of ovarian cancer." (PMID 33088217, 2020). "Therefore, PKP2/3 can potentially be identified as tumor biomarkers for early diagnosis and prognosis evaluation of ovarian cancer." (PMID 33088217, 2020). "We further explored the correlation of PKP2 expression with the prognosis in ovarian cancer." (PMID 33088217, 2020). "The results suggested that PKP2/3 may affect the survival and prognosis of ovarian cancer by regulating the immune infiltration in tumor microenvironment, which can provide new directions and novel approach for immunotherapy of ovarian cancer." (PMID 33088217, 2020). "Moreover, high expression of PKP2 was an independent risk factor affecting the survival and prognosis in ovarian cancer, suggesting that PKP2 may play a crucial role in occurrence, development and prognosis in ovarian cancer, and its potential mechanism needs to be further explored and validated." (PMID 33088217, 2020). "It was found that the incidence of amplifications in PKP2 was 6.27%, and PKP2 was related to the survival of patients with ovarian cancer, suggesting that the increase of gene amplification may be correlated with the prognosis of tumor." (PMID 33088217, 2020). "This study provides powerful evidences that PKP2/3 may affect the occurrence, development and biological behavior of ovarian cancer by regulating interacting proteins and signaling pathways." (PMID 33088217, 2020). "Among the most significant upregulated genes were plakophilin-2 (PKP2), which has been described as a Wnt/β-catenin target in colon cancer CAFs, and TIMP metallopeptidase inhibitor 3 (TIMP3), which was also highly upregulated in ovarian cancer CAFs." (PMID 39567960, 2024).
bladder cancer (4 papers, 2017 to 2023). "Similarly, the expression of PKP2, a desmosomal adhesions protein has been implicated in glioma and bladder cancer metastasis and high expression of Tescalcin, a gene thought to play a role in cell differentiation and implicated in invasive colorectal cancer." (PMID 29199959, 2017). "PKP2 expression is upregulated in many cancers, such as lung, ovarian, glioma, and bladder cancers." (PMID 35109912, 2022). "However, many studies have showed that PKP2 was decreased in some malignant tumors, such as gastric cancer and bladder cancer, and negatively correlated with the prognosis, proliferation and invasion of these tumors, indicating that PKP2 can also act as a tumor suppressor gene in malignant tumors." (PMID 33088217, 2020). "As yet, the role of PKP4 in bladder cancer is not known and other members of this family play a variable role, e.g., PKP2 is upregulated and PKP3 is downregulated in invasive bladder cancer." (PMID 36672328, 2023).
gastric cancer (4 papers, 2011 to 2025). A primary or metastatic malignant neoplasm involving the stomach. "In light of these data, we suggest that during gastric carcinoma progression, the loss of PKP2 and PKP3 expression correlates with an invasive phenotype." (PMID 21194493, 2011). "Previously, PKP2 was revealed to be highly expressed in various cancer types such as lung adenocarcinoma or gastric cancer, which was consistent with our results." (PMID 40872572, 2025). "In our cohort, we not only showed significantly decreased PKP2 immunoreactivity in gastric cancer tissue, but also found a significant correlation between decreased expression and a shortened DFS." (PMID 21194493, 2011). "Decreased PKP2 and PKP3 may be early prognostic markers and loss of PKP3 expression during gastric carcinoma progression may indicate an invasive phenotype." (PMID 21194493, 2011). "In our study, we examined PKP1, PKP2, and PKP3 expression and their clinicopathological correlation with gastric cancer." (PMID 21194493, 2011). "We explored the relationship between plakophilins (PKP1, PKP2, PKP3) to gastric cancer via immunohistochemical techniques." (PMID 21194493, 2011). "In gastric cancer, PKP1 expression was unchanged but PKP2 and PKP3 were significantly decreased as compared to normal controls." (PMID 21194493, 2011). "We observed cytoplasmic staining for PKP1, PKP2, and PKP3 in gastric carcinoma." (PMID 21194493, 2011).
long QT syndrome (4 papers, 2020 to 2024).
ventricular tachycardia (4 papers, 2018 to 2023). A disorder characterized by an electrocardiographic finding of three or more consecutive complexes of ventricular origin with a rate greater than a certain threshold (100 or 120 beats per minute are commonly used). "The 2 PKP2 VUS linked to “Ventricular Tachycardia” (Q59L and G327V) have a low allele frequency in GnomAD (0.00002 and 0.00009, respectively)." (PMID 30619891, 2018).
atopic dermatitis (3 papers, 2013 to 2021). "In several studies, the PKP2 gene was associated with canine atopic dermatitis, a chronic inflammatory skin disease." (PMID 34887490, 2021).
atrial fibrillation (3 papers, 2022 to 2024). A disorder characterized by an electrocardiographic finding of a supraventricular arrhythmia characterized by the replacement of consistent P waves by rapid oscillations or fibrillatory waves that vary in size, shape and timing and are accompanied by an irregular ventricular response. "Atrial fibrillation (ICD10 code I48) was associated with rare variation in 8 genes (TTN, RPL3L, KLF1, TET2, NME3, KDM5B, PKP2, PMVK)." (PMID 38390584, 2024). "Atrial fibrillation was associated with rare variations in 8 genes (TTN, RPL3L, KLF1, TET2, NME3, KDM5B, PKP2, PMVK)." (PMID 38390584, 2024). "Four of these genes have previously been linked in GWAS to atrial fibrillation (TTN, RPL3L, PKP2, PMVK)." (PMID 38390584, 2024).
colon cancer (3 papers, 2008 to 2024). "In PKP2, the exon inclusion form was shown to be the minor isoform in HT29, a colon cancer cell line." (PMID 18841251, 2008).
dilatation (3 papers, 2022 to 2025). "Clinical manifestations indicated similar LV dysfunction in LMNA, TTN, and PVneg patients, but greater LV dilatation and reduced systolic contraction in RBM20, and preserved LV with reduced RV function in PKP2." (PMID 35926050, 2022).
glioma (3 papers, 2017 to 2022). A benign or malignant brain and spinal cord tumor that arises from glial cells (astrocytes, oligodendrocytes, ependymal cells). "High expression of PKP2 was also associated with the prognosis and promoted proliferation and invasion in gliomas and lung adenocarcinomas, suggesting that PKP2 could promote tumor progression." (PMID 33088217, 2020).
lung adenocarcinoma (3 papers, 2020 to 2025). A carcinoma that arises from the lung and is characterized by the presence of malignant glandular epithelial cells. "Plakophilin-2 was shown to promote lung adenocarcinoma progression by enhancing EMT." (PMID 37580662, 2023).